TET2 (tet methylcytosine dioxygenase 2)
Diseases named in the same sentence as TET2 in open-access papers (continued):
Sharing a sentence is not in itself a finding about the gene and the disease.
chronic myelomonocytic leukemia (continued). "This is the case, for instance, of chronic myelomonocytic leukemia (CMML), a mixed MDS/MPN neoplasm where TET2 mutations are present in up to 60% of patients." (PMID 35159097, 2022). "The data suggest that TET2/DNMT3A mutations were present in many types of human malignancies and frequent in T cell lymphomas, chronic myelomonocytic leukemia and AML." (PMID 34039392, 2021). "TET2 mutations are detected in 7–23% of AML cases, 10–20% of MDS cases and 50% of chronic myelomonocytic leukaemia (CMML) cases." (PMID 31405121, 2019). "The Tet2 KO mice had expanded hematopoietic stem cell and progenitor cell populations, which induced disorders in myeloid and lymphoid cell lineages mimicking chronic myelomonocytic leukemia (CMML)." (PMID 39149518, 2024). "However, TET2 is one of the most mutated genes in AML, chronic myelomonocytic leukemia (CMML), and MDS." (PMID 36614080, 2022). "Some Tet2-deficient strains display progressive defects in myelopoiesis over a time course of 20 weeks, culminating in a myeloid neoplasia reminiscent of human CMML (chronic myelomonocytic leukemia)." (PMID 28408905, 2017). "We also searched for TET2, DNMT3A, ASXL1, EZH2, IDH1/2 and CBL gene families mutations, given their potential clinical importance in diseases closely associated with SM like primary myelofibrosis, chronic myelomonocytic leukemia (CMML) and others." (PMID 22905207, 2012). "TET2 mutations were subsequently identified in CD34‐positive progenitor cells in patients with MDS and chronic myelomonocytic leukemia (CMML), suggesting an early clonal origin." (PMID 40116537, 2025). "Loss of function mutations in TET2 have been reported in 20% of MDS and 50% of patients with chronic myelomonocytic leukemia (CMML)." (PMID 38028538, 2023). "For example, concomitant mutations of TET2 and SRSF2 are very frequent in chronic myelomonocytic leukemia (CMML)." (PMID 27029036, 2016). "Mutations involving epigenetic regulators (TET2~60% and ASXL1~40%) and splicing components (SRSF2~50%) are frequent in chronic myelomonocytic leukemia (CMML)." (PMID 26771811, 2016). "Furthermore, while TET2 mutations are more frequent in chronic myelomonocytic leukemia (CMML) than in AML, IDH1/2 mutations are more common in AML than in CMML." (PMID 33805247, 2021). "Among the three members of TET family genes (TET1, TET2, and TET3), TET1 chromosome translocation and TET2 mutations have been identified in hematopoietic malignancies such as AML and chronic myelomonocytic leukemia (CMML)." (PMID 34885145, 2021). "Patients with MDS who have more than one TET2 mutation have significantly increased monocyte counts in the bone marrow and peripheral blood, more specifically TET2I1873T mutation has been found to be significantly associated with progression to chronic myelomonocytic leukemia (CMML)." (PMID 38785456, 2024). "We hypothesize that the TET2- and PTPN11-related animals manifest features of FAB_M4/M5 rather than FAB_M0/M1/M2 since they are also hot mutations in chronic myelomonocytic leukemia and juvenile myelomonocytic leukemia (CMML and JMML)." (PMID 35771283, 2022). "However, TET2 mutations are relatively common in myeloid cancers and are present in 20–25% of MDS, 7–23% of AML, and up to 53% of chronic myelomonocytic leukemia (CMML) patients." (PMID 32526054, 2020). "With regard to HMT, TET2, DNMT3A and ASXL1 mutations have been reported to be associated with treatment response in MDS patients, but not in chronic myelomonocytic leukemia." (PMID 27419369, 2016). "Reduced TET2 activity and 5-hydroxymethylcytosine (5hmC) levels were observed in AML, MDS, chronic myelomonocytic leukemia (CMML), lymphoid leukemia, and other patients with hematological malignancies." (PMID 28407691, 2017).
melanoma (82 papers, 2013 to 2025). A malignant, usually aggressive tumor composed of atypical, neoplastic melanocytes. "It was also found that the loss of Tet2 acts in a cooperative manner with mutant NRas, driving melanoma genesis and accelerating melanoma progression." (PMID 40427015, 2025). "TET enzymes, particularly TET2, have been implicated in melanoma immune evasion and resistance to immune checkpoint inhibitors." (PMID 40427015, 2025). "In mouse models, loss of TET2 in myeloid progeny slowed melanoma growth by increased expression of proinflammatory M1 signatures and decreased expression of immunosuppressive M2 signatures." (PMID 41342736, 2025). "We previously reported the effect of VC in promoting checkpoint inhibitor immunotherapy efficacy using the B16-OVA melanoma syngeneic tumor model and that this is dependent on tumor-associated TET2 expression." (PMID 39388288, 2024). "Our prior research identified Ten-Eleven Translocation dioxygenase 2 (TET2) mediated loss of 5hmC marks as a functionally significant epigenetic hallmark of melanoma." (PMID 39091741, 2024). "TET2 is a tumor suppressor gene frequently mutated or down-regulated in melanoma, AML and many other types of cancers." (PMID 39091741, 2024). "Using the B16-OVA melanoma model, we previously demonstrated that TET2 is important for tumor-associated IFN-γ–regulated expression of chemokines CXCL9, -10, and -11." (PMID 39388288, 2024). "In serial sample analysis, we observed that mutations in DNMT3A and TET2 increased in size with longer ICB exposures in the melanoma cohort." (PMID 39456832, 2024). "In another study, TET2 was reported promoting tumor progression in melanoma via ARG1, an immunosuppressive gene in tumor-associated macrophages." (PMID 34957093, 2021). "Accordingly, it was recently found that ablation of the TET2 gene, resulting in genomic hmC loss, drives malignant transformation and melanoma progression." (PMID 32017278, 2020). "TET2-deficient macrophages altered the tumor microenvironment to reduce tumor burden during melanoma progression." (PMID 31001476, 2019). "In a separate study, TET2-deficient CD8+ tumor infiltrating lymphocytes (TILs) also displayed increased anti-tumor efficiency in a mouse model of melanoma." (PMID 31001476, 2019). "Activation of the IL-1R–MyD88 pathway leads to the up-regulation of tet2 in tumor-associated macrophages (TAMs) in melanoma mouse models and in patients with melanoma." (PMID 31557902, 2019). "Lastly, TET2 facilitated immunosuppression by tumor-infiltrating myeloid cells in a melanoma model and loss of TET2 in myeloid cells inhibited melanoma growth in vivo, consistent with the role of TET proteins in suppressing inflammation in myeloid cells." (PMID 30809228, 2019). "Regarding TET2, a study reported the association of the rs4698934 TET2 SNP with melanoma development whereas somatic mutations are rare in this disease." (PMID 28881727, 2017). "An SNP associated with melanoma risk was discovered in an intron of TET2, and somatic mutations of TET2 were reported in approximately 4% of melanoma cases in one study; however, other sequencing studies have not reported TET mutations." (PMID 28396701, 2017). "The loss of TET2 and its production of 5hmC are closely associated with diverse types of cancers, such as myeloid leukemia, melanoma, and colorectal, breast, liver, and lung cancers." (PMID 27821816, 2016). "Likewise, Bonvin and colleagues found a majority of melanoma samples in their study carried mutations in another TET gene in addition to TET2." (PMID 40116537, 2025). "Therefore, the Tet2 loss in a murine melanoma cell line conferred resistance to antitumor immunity mediated by CD8+ T-cells and immunotherapy." (PMID 40427015, 2025).
melanoma (continued). "Large genome‐wide association studies (GWAS) have reported associations between high‐frequency genomic variants localizing to the TET2 gene and the risk of several human cancers, including melanoma, breast cancer, colorectal cancer, endometrial cancer and prostate cancer (PCa)." (PMID 40116537, 2025). "Importantly, single-cell sequencing of preclinical samples and analysis of clinical data revealed that TET2/3-STAT1/3-CD274 signaling was associated with sensitivity to anti-PD1 treatment in melanoma." (PMID 36854755, 2023). "Genome-wide mapping of 5-hydroxymethylcytosine revealed its loss in melanoma, and restoring active TET2 or IDH2 reactivated 5-hydroxymethylcytosine suppressed melanoma growth and increased tumor-free survival in animal models, suggesting the therapeutic potential of targeting epigenetic changes." (PMID 31888295, 2019). "A previous study suggested that DNA methylation alterations in melanoma could be partly attributable to the dramatic loss of 5-hydroxymethylcytosine observed during malignant progression, caused by mutation of the TET2 enzyme coding gene." (PMID 28578692, 2017). "A recent study documented exceedingly rare somatic TET2 gene mutations in melanoma." (PMID 26221190, 2015). "It is important to highlight that widespread loss of 5-hmC is an additional epigenetic hallmark in IDH or TET2 mutated cancers, including melanoma, and that reestablishment of the 5-hmC landscape can suppress tumor invasion and growth in both melanoma cells and a zebrafish model." (PMID 24622842, 2014). "Importantly, overexpressing IDH2 or TET2 restored 5-hmc levels in melanoma cell lines, suggesting that lack/loss of function of these enzymes plays an essential role in 5-hmc depletion during melanoma progression." (PMID 28396701, 2017). "Restoring 5-hmc levels by IDH2 and TET2 overexpression was associated with suppressed tumor invasion and growth in a zebrafish melanoma model and mouse xenograft model of melanoma, suggesting a potential functional role of this epigenetic mark in melanoma growth and invasion." (PMID 28396701, 2017). "Moreover, TET2′s loss of production of 5hmC is a novel epigenetic hallmark for melanoma." (PMID 27821816, 2016). "Diminution of TET2 and reduction in 5hmC also correlate with poor survival and disease progression in mouse models of both melanoma and lung cancer." (PMID 40116537, 2025). "On the other hand, when normal melanocytes gain a malignant phenotype associated with melanoma, they suffer a decrease in the levels of TET enzymes, especially TET2, leading to a genome-wide loss of 5-hmC." (PMID 40427015, 2025). "It was demonstrated that HIF-1a silencing in a metastatic melanoma cell line led to a significant increase in the amount of TET2 enzyme, at both mRNA and protein levels." (PMID 40427015, 2025). "TET2 downregulation and low levels of 5-hmC represent hallmarks for melanoma progression, while another marker of aggressive malignant phenotype in melanoma is represented by the accumulation of the Hypoxia-Inducible Factor-1a (HIF-1a)." (PMID 40427015, 2025). "TET2-overexpression (OE) in cultured human melanoma cell lines resulted in a significant decrease in PRAME expression and this reduction is associated with increased 5hmC levels." (PMID 39091741, 2024). "By measuring the level of the Ki67 marker, complementary data revealed that exposure of melanoma cells to a stiff fibrin matrix activates the cell division cycle 42 (CDC42)/TET methylcytosine dioxygenase 2 (TET2) pathway and induces cell dormancy." (PMID 39682261, 2024). "Using single-cell RNA sequencing (scRNA-seq) analysis of the B16-OVA melanoma model, we have shown here that TET2 has an additional function in tumors, namely driving the expression of genes encoding proteins involved in antigen processing and presentation." (PMID 39388288, 2024). "In melanoma, our data show that it is most likely TET2-mediated 5hmC production that suppresses PRAME gene expression." (PMID 39091741, 2024).
melanoma (continued). "Expression of TAP1, TAPBP, and B2M was higher in 5hmC-high melanoma samples than 5hmC-low samples, indicating a positive correlation between TET2 activity and MHC I antigen-presenting genes." (PMID 39388288, 2024). "Here, we show that TET2 in B16-OVA melanoma tumor cells is important for expression of some MHC class I antigen presentation genes, including the key regulators TAP1 and TAPBP, which are regulated downstream of IFN-γ–induced signaling." (PMID 39388288, 2024). "Restoring 5hmC levels via TET2 overexpression notably reduced PRAME expression in melanoma cell lines." (PMID 39091741, 2024). "The finding of variable PRAME and 5hmC levels in MIS prompted us to explore a potential correlation between PRAME and TET2/5hmC levels in the premalignant to early malignant transitional phases of melanoma evolution." (PMID 39091741, 2024). "Next, we obtained multiple human malignant melanoma and colon adenocarcinoma tissue samples and stained for 5hmC as a marker for TET2 activity and for the key MHC I antigen-presenting genes TAP1, TAPBP, and B2M." (PMID 39388288, 2024). "Taken together, these results demonstrate that restoration of 5hmC marks by ectopic TET2 expression in cultured melanoma cells suppresses PRAME gene and protein expression levels." (PMID 39091741, 2024). "Our previous study showed that IFN-γ stimulated the binding between TET2 and STAT1 to activate target gene transcription, including those encoding chemokines, and we show here that in B16 melanoma cells INF-γ stimulates the interaction between TET2 and STAT1." (PMID 39388288, 2024). "We have previously reported that TET2 overexpression restores the 5hmC landscape along the genome of A2058 human melanoma cells and reduces tumor growth in vivo." (PMID 39091741, 2024). "In-depth analysis of melanoma’s epigenomic landscape uncovered a comprehensive loss of 5hmC, and the reintroduction of active TET2 or isocitrate dehydrogenase 2 (IDH2) in melanoma cells restored the 5hmC landscape and suppressed melanoma growth." (PMID 39519332, 2024). "TET2 is significantly down-regulated in melanoma as compared to melanocytes in healthy skin, 5-hmC levels are lower, and PRAME expression is higher." (PMID 39091741, 2024). "In a recent study using a melanoma mouse model, TET2 expression promoted suppressive TAM genetic profiles and suppressive myeloid cell activities." (PMID 38426087, 2024). "In another melanoma mouse model, TET2 depletion increased AKT and proliferation marker expression, decreased cell cycle inhibitors, and accelerated tumor development." (PMID 38426087, 2024). "The authors concluded that TET2 acts as a barrier to melanoma initiation and progression, partly by promoting 5hmC gains in specific gene bodies." (PMID 37834158, 2023). "In fact, previous studies reported overexpression of TET2 in colorectal carcinoma, glioblastoma, melanoma cells, and chronic lymphocytic leukaemia patients." (PMID 36989121, 2023). "In a murine melanoma model, TET2 deletion in myeloid cells resulted in reduced tumor burden and increased tumor-infiltrating T cells suggesting that TET2 promotes a myeloid immunosuppressive program in the tumor microenvironment." (PMID 37841428, 2023). "In a mouse model with NRAS-driven melanomagenesis, Tet2 cooperated with oncogenic NRASQ61K to promote melanoma initiation while suppressing specific gains in 5hmC." (PMID 37834158, 2023). "To further corroborate the link between α-KG-TET2/3 and PD-L1, we treated melanoma cells with dm-α-KG, and the results showed that α-KG promoted the protein expression of PD-L1 and TET2/3 in melanoma cells." (PMID 36854755, 2023). "In murine and human melanoma specimens, TET2 expression is increased in tumor associated macrophages (TAM), indicating the oncogenic function of TAM via TET2 modification." (PMID 37928272, 2023).
melanoma (continued). "In a mouse melanoma model, knockdown of TET2 in overtly metastatic OT-I cells resulted in delayed melanoma progression, with a reduction in tumor size of up to 80%." (PMID 37781382, 2023). "For example, DNA demethylase TET2 promotes melanoma progression by maintaining the immunosuppressive function of myeloid cells and enhances anti-tumor immunity by governing G-MDSCs and CD8 + T-cell numbers." (PMID 36091162, 2022). "Targeted deletion of the TET2 gene within murine melanoma cells highlighted also consequences on the immune system with a reduced T cell infiltration of the mutated tumor." (PMID 35663987, 2022). "A previous study has shown that in melanoma and colon tumors, both PD-L1 and chemokine genes are silenced by DNA methylation and are activated by TET2-mediated demethylation after inflammation and IFN-γ stimulation." (PMID 35173532, 2022). "Our results are in line with those of another study where significantly reduced levels of 5-hmC and TET2 in advanced melanomas compared to nevi and thin melanomas were reported." (PMID 34198758, 2021). "Rebuilding the 5-hmC landscape in melanoma cells by reintroducing active TET2 or IDH2 suppressed melanoma growth and increased tumor-free survival in animal models." (PMID 34198758, 2021). "Both in conjunctival nevi and melanomas, the level of TET2 expression was low (score ranging from 0 to 1, rarely 2)." (PMID 34198758, 2021). "TET2 L1721W mutation was recurrent in cancer cell lines derived from carcinomas of the breast, NSCLC, melanoma, renal, prostate, and was reportedly detected in patients with MDS." (PMID 34039392, 2021). "TET2 expression is elevated in tumor infiltrating myeloid cells of both melanoma patients and mouse models via the IL-1R-MyD88 pathway." (PMID 33535484, 2021). "Adoptive transfer of TET2 knocked out (TET2 KO) CD8+ T cells to murine melanoma tumor model showed significant tumor regression and a significant increase of TET2 KO CD8+ T cell population in the tumor, spleen, and peripheral blood." (PMID 35087832, 2021). "Cell survival was significantly inhibited by T-dCyd in breast BT549, lung NCI-H23, melanoma SKMEL5 and renal ACHN cancer lines harboring deleterious TET2 and nonsynonymous DNMT3A mutations compared to 13 lines without such mutation pattern (P = 0.007)." (PMID 34039392, 2021). "In the melanoma mouse model, ten-eleven-translocation-2 (Tet2) is found to be up-regulated on TAMs through IL-1R-MyD88 signaling." (PMID 34625124, 2021). "At the functional level, the authors of this study demonstrated in two different animal models that restoring the function of IDH1 or TET2 not only restored the level of 5-hmC in melanoma, but also reduced tumor growth." (PMID 34198758, 2021). "TET2 expression is increased in intratumoral myeloid cells, both in a mouse model of melanoma and in melanoma patients, that is dependent on an IL-1R-MyD88 pathway." (PMID 32486098, 2020). "Pan and colleagues demonstrated that Tet2 promoted the progression of mouse melanoma by maintaining the myeloid cells that exerted immunosuppressive functions in the tumor microenvironment." (PMID 32014008, 2020). "In particular, Tet2 transcript was found to be increased in TAMs, both in murine in vivo melanoma models (subcutaneous injection of YUMM1.7 and B16-OVA cell lines) and in human peripheral blood and melanoma tissue samples." (PMID 33212945, 2020). "During melanoma growth, Tet2 expression is enhanced in myeloid-derived suppressor cells (MDSCs) and TAMs39." (PMID 33184433, 2020). "Supplementation of ascorbic acid in melanoma cell lines with TET2 knockdown resulted in an increase in 5-hmC." (PMID 33352824, 2020). "Deletion of Tet2 in tumor-infiltrating myeloid cells of melanoma-bearing mice (Mye-Tet2 null mice) led to a significant suppression of in vivo tumor growth, compared to wild-type mice." (PMID 33212945, 2020).